DNASE1L3 (deoxyribonuclease 1L3)
Diseases named in the same sentence as DNASE1L3 in open-access papers (continued):
Sharing a sentence is not in itself a finding about the gene and the disease.
colon cancer (5 papers, 2020 to 2026). "In mice, Dnase1l3 deficiency in the tumor microenvironment enhances tumor formation and growth in several colon cancer models." (PMID 37581941, 2023). "Collectively, our data from 2 independent colon cancer models demonstrate that Dnase1l3 deficiency in mice promotes tumorigenesis." (PMID 37581941, 2023). "By analyzing the TME components of colon cancer in the TCGA database, we found that the expression of DNASE1L3 is decreased in colon cancer and it is associated with prognosis, disease progression, and immune invasion in colon cancer." (PMID 34157681, 2021). "In conclusion, this study reveals that DNASE1L3 may be an important biomarker associated with immune infiltration in colon cancer and will provide a theoretical basis for the selection of immunotherapy targets for colon cancer." (PMID 34157681, 2021). "Therefore, we concluded that DNASE1L3 might be a biomarker associated with prognosis and immune infiltration in colon cancer." (PMID 34157681, 2021). "In this study, we identify DNASE1L3 as a potentially new regulator of antitumor immunity and a tumor suppressor in colon cancer." (PMID 37581941, 2023). "In order to explore the effect of DNASE1L3 on the function of colon cancer cells, the Western blot was used to detect the basic protein expression of DNASE1L3 in 5 colon cancer cell lines: SW480, SW48, HT-29, HCT-116 and SW620." (PMID 34157681, 2021). "Gene Expression Omnibus (GEO) validation cohorts (GSE40967 and GSE23878) also showed a significant decrease in DNASE1L3 expression in colon cancer compared with normal tissue." (PMID 34157681, 2021). "In the Cancer Genome Atlas (TCGA) database, we compared DNASE1L3 expression of colon cancer samples with normal samples at the mRNA level and found that DNASE1L3 expression was significantly lower in the tumor group than in the normal group." (PMID 34157681, 2021). "Based on protein expression result, SW480 and SW48 cells with the lowest expression of DNASE1L3 among the 5 colon cancer cells were selected for subsequent cell function experiments." (PMID 34157681, 2021). "Validation results from multiple databases showed low expression of DNASE1L3 in colon cancer." (PMID 34157681, 2021). "This suggests that DNASE1L3 may regulate colon cancer immunity by regulating multiple immune cell groups." (PMID 34157681, 2021). "These suggested that DNASE1L3 was under-expressed in colon cancer tissues." (PMID 34157681, 2021). "It was found that DNASE1L3, ITGA5, BRAP, and NFE2L2 were related to the immune infiltration of colon cancer." (PMID 35252219, 2021). "Moreover, DNASE1L3 has been identified as a potential prognostic biomarker in LUAD and colon cancer." (PMID 41523912, 2026). "To further elucidate how an early-phase activation of proinflammatory responses leads to a late-phase reduction of antitumor immunity in the colon of Dnase1l3-KO mice, we established a syngenic colon tumor model by s.c. injecting MC38 murine colon cancer cells into Dnase1l3 WT and Dnase1l3-KO mice." (PMID 37581941, 2023). "In this study, we found that DNASE1L3 had a negative correlation with the prognosis of colon cancer patients and was gradually downregulated with the progression of the disease." (PMID 34157681, 2021).
glomerulonephritis (4 papers, 2023 to 2024). A renal disorder characterized by damage in the glomeruli. "In conclusion, both Dnase1-/- x Siglecg-/-, as well as Dnase1l3-/- x Siglecg-/- aging mice developed glomerulonephritis, with a more severe disease score detected in the latter mouse line." (PMID 36969253, 2023). "We checked for the intersection of the list of the SLE with DNASE1L3 deficiency up-DPpGCs and the gene variants in the GWAS catalog of terms related with SLE and glomerulonephritis." (PMID 37048133, 2023). "Histological analysis of the kidneys revealed glomerulonephritis in both Siglecg-/- x Dnase1-/- and Siglecg-/- x Dnase1l3-/- mice, but with a stronger glomerular damage in the latter." (PMID 36969253, 2023).
colorectal cancer (3 papers, 2021 to 2025). A primary or metastatic malignant neoplasm that affects the colon or rectum. "Interestingly, the downregulation of DNASE1L3 expression was commonly seen across various cancer types such as colorectal cancer, lung cancer, nasopharyngeal carcinoma, and head and neck squamous cell carcinoma, supporting the potential decline of DNASE1L3 in patients with cancers." (PMID 35454026, 2022).
COVID-19 (3 papers, 2022 to 2024). A disease caused by infection with severe acute respiratory syndrome coronavirus 2. "Altogether, our findings suggest that severe COVID-19 is linked to defects in DCs and pDCs, which may explain the inadequate production of DNase1L3 needed to clear NET complexes." (PMID 38454482, 2024). "Like the pediatric samples, these results indicate that the impairments in NET degradation in adults with COVID-19 are multifactorial and may be associated with the presence of autoAbs against DNase1L3 and elevated levels of G-actin." (PMID 35852866, 2022). "We investigated DNASE1L3 gene expression in pDCs and DCs using publicly available single-cell RNAseq data from 80 COVID-19 patients." (PMID 38454482, 2024). "Our research reveals a pronounced dysregulation in the balance between DNase1L3 antigen and the amount of NETs in hospitalized COVID-19 patients." (PMID 38454482, 2024). "Further studies are necessary to determine the precise contribution of DNases to degrade free DNA and NETs, with specific assessment of DNase1 and DNase1L3 activities in COVID-19 patients with varying disease severity." (PMID 38454482, 2024). "Analysis of public single-cell RNAseq data revealed reduced DNase1L3 expression in pDCs from severe COVID-19 patient." (PMID 38454482, 2024). "A pursuit to uncover why circulating DNase levels did not increase in proportion to NETosis during severe or critical COVID-19 led to the hypothesis that genetic variations in DNASE1 and DNASE1L3 genes might be responsible for the deficiency in DNase amount or function." (PMID 38454482, 2024). "Collectively, it appeared that circulating DNase1 and DNase1L3 were not sufficiently upregulated to eliminate the NETs formed in severe and critical COVID-19 patients." (PMID 38454482, 2024). "Our investigation extended to understanding why circulating DNase1 and DNase1L3 were not efficiently upregulated during severe and critical COVID-19." (PMID 38454482, 2024). "COVID-19-affected adults displayed significant prevalence of impaired NET degradation, in association with anti-DNase1L3, G-actin, and specific disease manifestations, but not with genetic variants of DNases." (PMID 35262093, 2022).
renal clear cell carcinoma (3 papers, 2021 to 2026). "Previous studies have identified associations between DNASE1L3 and signaling pathways in breast cancer and the staging of renal clear cell carcinoma." (PMID 41523912, 2026). "In addition, investigators announced that the expression level of DNASE1L3 is closely align with the stage of clear cell renal cell carcinoma." (PMID 34868195, 2021).
systemic sclerosis (3 papers, 2014 to 2023). A chronic disorder, possibly autoimmune, marked by excessive production of collagen which results in hardening and thickening of body tissues. "DNASE1L3 was also recently identified as a risk gene in systemic sclerosis." (PMID 25620976, 2014). "As such, it is also not surprising that a lack of DNASE1L3 has been associated with systemic sclerosis in previous studies." (PMID 38034352, 2023).
anemia (2 papers, 2021 to 2023). A reduction in the number of red blood cells, the amount of hemoglobin, and/or the volume of packed red blood cells. "Antibodies to DNase1L3 were significantly associated with anemia, livedo, proteinuria, low complement levels, use of cytotoxic treatment, and a broad range of autoantibodies, including anti-dsDNA, anti-cardiolipin, lupus anticoagulant, anti-β2-glycoprotein I (B2GPI), anti-Ro52 antibodies." (PMID 36941260, 2023).
complement deficiencies (2 papers, 2016 to 2021). "With the exception of DNase1, DNase1L3, PRKCD deficiencies and complement deficiencies (for which no information on IFN expression is available), an increase in type I IFN activity was documented in the most part of affected patients." (PMID 27260006, 2016).
dermatomyositis (2 papers, 2020 to 2025). Dermatomyositis (DM) is a type of idiopathic inflammatory myopathy characterized by evocative skin lesions and symmetrical proximal muscle weakness. "In this study, we aimed to ascertain the involvement of the extracellular nucleases, specifically DNase1l3 and DNase-1, in the cfDNA profiles of dermatomyositis patients." (PMID 40599779, 2025).
nephritis (2 papers, 2010 to 2021). Inflammation of renal tissue. "Perhaps the activity of DNASE1L3 in the close vicinity of renal, hepatic, and pulmonary endothelial cells protects against the development of nephritis and other forms of vasculitis at these sites." (PMID 34200671, 2021). "A tendency for gradual elevation of Dnase1l3 expression with nephritis progression was observed, however, no formal statistical significance was reached when either parametric (ANOVA) or non-parametric (Kruskal-Wallis) tests were applied." (PMID 20856893, 2010).
periodontitis (2 papers, 2024 to 2025). An acute or chronic inflammatory process that affects the tissues that surround and support the teeth. "DNASE1L3- deoxyribonuclease 1 like 3 may contribute to the inflammatory response that destroys periodontal tissue and can cause vascular occlusion in periodontitis." (PMID 38532421, 2024). "IGLJ3, DNASE1L3, ABCG1, DPEP2, and KIF19 are highly differentiated genes associated with diabetes and periodontitis." (PMID 38532421, 2024). "Other significant genes included DNASE1L3, CDKL1, and DPEP2, highlighting the compounding effects of poor glycemic control, dyslipidemia, and periodontitis on molecular dysregulation." (PMID 40458179, 2025).
Sepsis (2 papers, 2024). Sepsis is defined as life-threatening organ dysfunction caused by a dysregulated host response to infection. "Another potential explanation for the accumulation of NETs and the reduction of ROS is that the loss of DNase1 and DNase1L3 impairs their protective impact on the pathogens during sepsis." (PMID 38612596, 2024). "Under sepsis conditions, the liver, lung, and intestines of PAD4-KO mice showed a somewhat increased expression of DNase1 and DNase1L3, when compared to WT mice in response to sepsis." (PMID 38612596, 2024). "DNase1 and DNase1L3 play pivotal roles in the regulation of DNase activity in plasma, crucial for maintaining the integrity of blood and tissues during sepsis." (PMID 38454482, 2024). "Our experiments revealed the increased expression of DNase1 and DNase1L3 in PAD4-KO, compared to WT mice, in almost all three sepsis models." (PMID 38612596, 2024). "The absence of DNase1 and DNase1L3 has been demonstrated to result in severe vascular occlusions in a sepsis model, underscoring the critical importance of controlled NETosis." (PMID 38454482, 2024). "Notably, in mice lacking both DNase1 and DNase1L3, the induction of septicemia results in intravascular NET clot formation, leading to vessel occlusion and eventual mortality." (PMID 38454482, 2024).
acne inversa (1 paper, 2023). "Similarly, combined deficiency in DNase1 and DNase1L3 due to neutralizing auto-antibodies, impairs NET clearance and underlies the inflammatory skin disorder hidradenitis suppurativa (acne inversa, 49)." (PMID 37287977, 2023).
adenoma (1 paper, 2023). A neoplasm arising from the epithelium. "Histopathological evaluations of the colons from AOM/DSS-treated mice further revealed that Dnase1l3-KO mice had more advanced tumors (adenoma and adenocarcinoma) compared with WT mice, whose tumors had characteristics of atypical hyperplasia." (PMID 37581941, 2023).
Aicardi–Goutières syndrome (1 paper, 2024). "The most common T1Is that feature SLE phenotypes comprise DNASE1L3 and DNASEII deficiencies, COPA (coatomer subunit-α) syndrome, Aicardi–Goutières syndrome (AGS), and STING-associated vasculopathy with onset in infancy (SAVI)." (PMID 39135943, 2024).
Alzheimer disease (1 paper, 2024). A progressive, neurodegenerative disease characterized by loss of function and death of nerve cells in several areas of the brain leading to loss of cognitive function such as memory and language. "In addition, DNase, a commonly used NETs inhibitor, has been successfully applied in the treatment of Alzheimer’s disease, and genetic variants in DNase genes including DNASE1, DNASE2 and DNASE1L3 can result in the downregulation of DNase expression in Alzheimer’s disease." (PMID 38188146, 2024).
Arterial thrombosis (1 paper, 2023). The formation of a blood clot inside an artery. "Although this study did not focus on the analysis of anti-phospholipid syndrome, it is worth noting that anti-DNase1L3 antibody positivity was significantly associated with livedo, lupus anticoagulant, antibodies to cardiolipin and B2GPI, and marginally with arterial thrombosis." (PMID 36941260, 2023).
asthma (1 paper, 2020). "Gene expression of DNASE1L3 (P = .045) was upregulated in asthma compared with HC, and IL1B (P = .017) was upregulated in neutrophilic asthma compared with non‐neutrophilic asthma." (PMID 31903716, 2020). "DNASE1L3 is increased during apoptosis and plays an important role in fragmentation of DNA from the apoptotic vesicles; our results might be reflective of an overall increase of cellular apoptosis in participants with asthma." (PMID 31903716, 2020). "Similar patterns of expression of known gene signatures were observed in endobronchial biopsies characterized by the upregulation of DNASE1L3 in asthma and IL1B in neutrophilic asthma suggesting these pathways are relevant in both biopsy and sputum in asthma." (PMID 31903716, 2020).
atherosclerosis (1 paper, 2025). A disease characterized by the build-up of fatty material and calcium deposition in the arterial wall resulting in partial or complete occlusion of the arterial lumen.
cervical cancer (1 paper, 2024). A primary or metastatic malignant neoplasm involving the cervix. "Considering that there is a significant downregulation of motifs starting with “C” in non‐responders, we further explored the expression of DNASE1L3 in cervical cancer and its impact on chemotherapy sensitivity and tumor progression." (PMID 39319610, 2024). "The results showed a similarly significantly lower DNASE1L3 expression in cervical cancer samples when compared to normal cervical samples, which suggested that the dysregulation of DNASE1L3 may play a role in the development and progression of cervical cancer." (PMID 39319610, 2024).
colorectal tumors (1 paper, 2023). "Further bioinformatic analyses revealed that several immune cell markers, including CCR7, CD40LG, and CD3G, were among the most positively correlated genes with DNASE1L3 in human colorectal tumors, indicative of a possible association between DNASE1L3 expression and antitumor immune activity." (PMID 37581941, 2023).
cystic fibrosis (1 paper, 2022). Autosomal recessive disorder caused by pathogenic variants in the CFTR gene (cystic fibrosis transmembrane conductance regulator), which encodes a chloride and bicarbonate channel expressed in epithelial cells, and follow the diagnosis criteria. "The enzymatic activity of nucleases such as Dnase1 and Dnase1L3 are particularly important in diseases such as cystic fibrosis." (PMID 35974043, 2022).
follicular lymphoma (1 paper, 2015). Follicular lymphoma is a form of non-Hodgkin lymphoma characterized by a proliferation of B cells whose nodular structure of follicular architecture is preserved. "The other genes, such as HK2, CENPF, CTPS, LDHA, P2RY5 and DNASE1L3 also can be identified in both transformation follicular lymphoma and ‘indolent’ type FL." (PMID 26416427, 2015).
glomerulosclerosis (1 paper, 2023). A hardening of the kidney glomerulus caused by scarring of the blood vessels. "However, both Dnase1-/- x Siglecg-/- and Dnase1l3-/- x Siglecg-/- mice revealed a significantly increased mean glomerulosclerosis index compared to Dnase1-/- and Dnase1l3-/- single knockout mice." (PMID 36969253, 2023).
Hepatitis (1 paper, 2021). Inflammation of the liver. "Since DNASE1L3 is also an extracellular secreted protein, furthermore, we analyzed plasma DNASE1L3 protein levels in another cohort of 95 cases encompassing 50 inoperable HCC patients, 27 patients with hepatitis only and 18 healthy individuals." (PMID 33744849, 2021).
Immunodeficiency (1 paper, 2023). Failure of the immune system to protect the body adequately from infection, due to the absence or insufficiency of some component process or substance. "However, CD8+ T cells from MC38 tumors in Dnase1l3-KO mice also had significantly higher expression of several genes important in T cell activation, differentiation, and immunodeficiency." (PMID 37581941, 2023).
intestinal cancer (1 paper, 2023). "Dnase1l3 deficiency impairs tissue recovery and increases susceptibility to intestinal cancer formation." (PMID 37581941, 2023).
intestinal tumors (1 paper, 2023). "To further confirm these observations, we bred Dnase1l3-deficient mice to APCmin/+ mice, which develop spontaneous intestinal tumors driven by deregulated β-catenin signaling." (PMID 37581941, 2023).
kidney damage (1 paper, 2023). "In addition, the blood urea nitrogen (BUN) content was examined in aging Dnase1-/-, Dnase1-/- x Siglecg-/-, Dnase1l3-/- and Dnase1l3-/- x Siglecg-/- mice, Siglecg-/- mice and wt mice to examine the consequences of kidney damage." (PMID 36969253, 2023).
lung adenocarcinoma (1 paper, 2021). A carcinoma that arises from the lung and is characterized by the presence of malignant glandular epithelial cells. "In a word, this is the first study to comprehensively analyze the relationship between DNASE1L3 expression level and early diagnosis and prognosis in patients with lung adenocarcinoma." (PMID 34868195, 2021). "We speculate that the down expression of DNASE1L3 in lung adenocarcinoma is highly likely to be related to the abnormal regulation of m6A-related regulators; of course, the clear mechanism needs to be further studied." (PMID 34868195, 2021). "However, the diagnosis and prognosis roles of DNASE1L3 gene in lung adenocarcinoma (LUAD) remain largely unknown." (PMID 34868195, 2021).
lymphoma (1 paper, 2021). A malignant (clonal) proliferation of B- lymphocytes or T- lymphocytes which involves the lymph nodes, bone marrow and/or extranodal sites. "One study suggested that DNASE1L3 deficiency may cause lymphoma cells to become resistant to VP-16." (PMID 34157681, 2021).
ovarian carcinoma (1 paper, 2013). A malignant neoplasm originating from the surface ovarian epithelium. "The anti-EGFRvIII and anti-EGFR antibody guided vectors delivered the DNA constructs for DNase1, DNase1L3, DNase2, DFFB into the nuclei of the human EGFRvIII and EGFR over-expressing ovarian cancer cells from ascites and cultures." (PMID 24587967, 2013).
Splenomegaly (1 paper, 2023). Abnormal increased size of the spleen. "At the recovery phase following the first DSS treatment (D19), Dnase1l3-KO mice also had reduced colon length and impaired recovery of tissue damage, and they showed splenomegaly, as previously reported." (PMID 37581941, 2023).
steatosis (1 paper, 2025). Increased lipid within the cytoplasm of cells. "Using multi-omics analyses combined with immunophenotyping, we demonstrate that Dnase1l3-deficient (knockout, KO) mice exhibit disrupted myeloid differentiation, Kupffer cell M1 polarization (M1), and progressive hepatic steatosis." (PMID 41458908, 2025).